INS (insulin)
Diseases named in the same sentence as INS in open-access papers (continued):
Sharing a sentence is not in itself a finding about the gene and the disease.
Insulin resistance (continued). "It has been reported that PIO improves insulin resistance through a reduction in oxidative stress and inflammation, and enhances insulin sensitivity in a T2DM rat model induced by a high-carbohydrate diet." (PMID 40076566, 2025). "Insulin resistance has been defined as an attenuated biological response to circulating insulin levels or impaired sensitivity to insulin mediated glucose disposal." (PMID 41437079, 2025). "The overexpression of VEGF-A protects against insulin resistance, and insulin stimulates the production of VEGF-A." (PMID 41007744, 2025). "S6K1 has been shown to integrate nutrients and insulin signals, since S6K1 reduction and inhibition has been shown to cause glucose intolerance and insulin resistance." (PMID 39747664, 2025). "Skeletal muscle's pivotal role in glucose homeostasis and insulin resistance in T2D is well established, underscored by persistent defects in insulin-stimulated glucose uptake and mitochondrial oxidation in myocytes obtained from individuals with T2D." (PMID 40495716, 2025). "This inflammatory response exacerbates insulin resistance, creating a detrimental feedback loop that perpetuates hyperglycemia-induced insulin resistance." (PMID 40149685, 2025). "It will also be important to understand the effect of chronically high insulin levels seen during the development of insulin resistance and to uncover the mechanisms by which insulin signaling in microglia alters behavior to affect food intake." (PMID 41163155, 2025). "Upregulation of the IRS-1 pathway in the three key insulin target tissues is related to insulin resistance and impaired glucose metabolism, including gluconeogenesis and glycogen synthesis." (PMID 40729355, 2025). "Insulin resistance, common in CKD, diminishes the anabolic effects of insulin on muscle tissue, while vitamin D deficiency is linked to muscle weakness and atrophy." (PMID 40144877, 2025). "Insulin resistance is increased, as indicated by insulin tolerance testing, while insulin levels during glucose tolerance testing remain unaffected." (PMID 40868906, 2025). "TNF-α can also directly affect muscle protein degradation and can contribute to the development of insulin resistance by reducing insulin-regulated glucose transporter levels and impairing the insulin signaling pathway." (PMID 40869715, 2025). "In obese individuals with insulin resistance, insulin continued to reduce urinary sodium excretion, suggesting that insulin’s capacity to promote salt absorption remains intact." (PMID 40725728, 2025). "Dysfunctional mitochondria within insulin-sensitive tissues, such as skeletal muscle and adipose tissue, significantly contribute to insulin resistance and the progression of T2DM." (PMID 40862129, 2025). "T1DM is an autoimmune destruction of beta cells, which usually leads to insulin deficiency, while T2DM is a frequent progressive decrease in beta cell insulin secretion and insulin resistance." (PMID 40248148, 2025). "↓ Blood glucose, ↓ insulin levels, ↓ insulin resistance, ↓ HOMA-IR, ↑ GLP-1, preserved pancreatic β-cells integrity and function, ↓ liver MDA levels, ↑ liver SOD, CAT, and GSH levels, improved lipidic metabolism, anti-inflammatory activity." (PMID 40722870, 2025). "As a result, the authors identified mTORC1-dependent phosphorylation of S377 on AMPKα2 as a core substrate that is defective in insulin resistance, and S441 on MINDY1 as a protein associated with increases in insulin sensitivity after exercise." (PMID 40604168, 2025). "This leads to insulin resistance, augmented hepatic gluconeogenesis, accelerated glycogenolysis, and relatively insufficient insulin secretion." (PMID 40646492, 2025). "Insulin resistance diminishes the liver’s response to insulin, disrupting glucose and lipid metabolism, while leptin resistance leads to energy imbalance, further exacerbating hepatic lipid accumulation." (PMID 40538532, 2025).
Insulin resistance (continued). "Fasting insulin levels and the homeostasis model assessment of insulin resistance (HOMA-IR) are widely used markers to assess insulin sensitivity and the presence of insulin resistance—key determinants of metabolic health." (PMID 39940866, 2025). "The GH excess impairs insulin signaling and promotes lipolysis, leading to increased levels of free fatty acids which contributes to insulin resistance and development of DM." (PMID 40622518, 2025). "This reaction induces the production of insulin autoantibodies, leading to various clinical manifestations such as insulin resistance, hyperglycemia, recurrent hypoglycemic episodes, and allergic reactions." (PMID 41585798, 2025). "Toll-like receptor 4 (TLR4) significantly contributes to the onset of insulin resistance (IR) and inflammation, being expressed in insulin-responsive tissues." (PMID 40881124, 2025). "The results showed that compared with the Mediterranean diet, the high-protein diet was more effective in reducing insulin resistance and improving blood glucose variability, further illustrating that a high-protein diet can improve insulin efficacy." (PMID 40045263, 2025). "Second, UPFs often contain additives, such as carrageenan, which has been shown to impair insulin signaling and promote insulin resistance, a key driver of NAFLD." (PMID 40717999, 2025). "Increased in obese or overweight PCOS patients.Fetuin-A can contribute to insulin resistance in PCOS patients by inhibition of the insulin signaling pathway and activation of inflammatory pathways." (PMID 39858445, 2025). "All these factors contribute to the development of insulin resistance and increased concentrations of insulin and C-peptide." (PMID 40559402, 2025). "Insulin resistance was estimated using the homeostasis model assessment of insulin resistance calculated from fasting glucose and fasting insulin values." (PMID 41156497, 2025). "Obesity and insulin resistance are frequently associated with menstrual irregularities in adolescents, and PCOS is uniquely characterized by disturbances in both insulin and lipid metabolism." (PMID 40861046, 2025). "The disease progression is invariably accompanied by decreased insulin production and/insulin resistance, altered lipid metabolism, dyslipidemia, which can lead to atherogenesis and elevated risk of atherosclerotic cardiovascular disease (ASCVD)." (PMID 40896083, 2025). "Metabolic parameters such as fasting glucose, insulin, homeostatic model assessment for insulin resistance (HOMA-IR), and lipid profile were evaluated." (PMID 40792318, 2025). "The first paradigm, gene addition, focuses on delivering functional insulin or insulin-sensitizing transgenes to compensate for β-cell failure or peripheral insulin resistance." (PMID 41226304, 2025). "In adipose tissue, RAAS contributes to and worsens insulin resistance by disrupting insulin-mediated glucose uptake and generating reactive oxygen species, which further impair insulin signaling." (PMID 40725728, 2025). "A galactose + high-fat diet and oxidative stress contribute to the onset of insulin resistance, and the inhibition of insulin secretion leads to hyperglycemia." (PMID 40573255, 2025). "In our model, isoespintanol-treated rats had improved insulin resistance and normalized in vitro insulin secretion, probably involving the IR-PI3K-AKT pathway." (PMID 40094747, 2025). "The metabolic score for insulin resistance (METS-IR), a clinical surrogate marker for obesity-related insulin resistance (IR), was developed by Mexican researchers to assess insulin sensitivity." (PMID 41404507, 2025). "T2DM is a chronic metabolic condition primarily characterized by insulin resistance (IR) and a reduction in insulin production." (PMID 40612440, 2025). "They observed that saturated fatty acid, palmitate (C16), tends to induce insulin resistance, whereas unsaturated fatty acids, oleate (C18:1) and linoleate (C18:2), improve insulin sensitivity." (PMID 41462795, 2025).
Insulin resistance (continued). "Insulin resistance was defined as the inability of insulin to optimally stimulate glucose transport to body cells (hyperinsulinemia or impaired glucosetolerance)." (PMID 40078029, 2025). "In individuals with insulin resistance insulin signaling is impaired at the level of Insulin Receptor Substrate-1 (IRS-1), leading to decreased glucose transport/phosphorylation/metabolism and impaired nitric oxide synthase activation/endothelial dysfunction." (PMID 41009753, 2025). "Consistently, a rapid glucose response to insulin load was not evident in HFD-fed rats after overexpressing IREB2, inhibiting insulin sensitivity while increasing the Homeostatic Model Assessment for Insulin Resistance (HOMA-IR) score." (PMID 39910919, 2025). "Overall, these experiments reveal that LL:AA mice exhibit systemic insulin resistance primarily driven by impaired insulin sensitivity of skeletal muscle, and possibly liver, with compensatory increases in adiposity over time." (PMID 41004571, 2025). "Insulin resistance is characterized by the body’s failure to respond to the physiological activity of insulin." (PMID 40076851, 2025). "It has been shown that the short arm of chromosome 3 has a strong linkage to serum insulin concentrations and fasting insulin resistance index." (PMID 41328998, 2025). "Insulin resistance was calculated using the HOMA-IR formula: [fasting insulin (μU/mL) × fasting glucose (mg/dL)]/405." (PMID 40951687, 2025). "The ketogenic diet can significantly improve weight management and insulin sensitivity, which is particularly important for PCOS patients, as PCOS is often associated with insulin resistance and obesity." (PMID 41377049, 2025). "The results showed that quercetagetin and lutein, either alone or in combination, reduced elevated fasting blood glucose and insulin levels, enhanced glucose and insulin tolerance, and alleviated insulin resistance." (PMID 41464985, 2025). "Liver-specific IDE knockout (L-IDE-KO) mice exhibit insulin resistance and glucose intolerance despite normal insulin levels and preserved β-cell function." (PMID 40724942, 2025). "miR-16, 106-5p, 222-3p, 375, and 7218-5p are known to target pancreatic β-cells and affect insulin secretion, while miR-27a, 29a, 155, 222, and 802-5p target skeletal muscle and contribute to insulin resistance." (PMID 41446634, 2025). "The most widely used index for assessing insulin sensitivity is the homeostatic model assessment of insulin resistance (HOMA-IR)." (PMID 40283451, 2025). "Reduced NO bioavailability impairs vasodilation, decreases insulin-mediated glucose uptake, and contributes to insulin resistance." (PMID 40564010, 2025). "The current study revealed a significant association between apolipoproteins and various metabolic parameters such as body weight, BMI, body fat percentage, blood glucose, insulin levels, and insulin resistance." (PMID 40123054, 2025). "Insulin resistance parameters (glucose, insulin, HBA1c) of the individual with type 1 diabetes were ruled out." (PMID 40136618, 2025). "The KD can significantly improve insulin sensitivity, which is particularly relevant in conditions like insulin resistance, NAFLD, and type 2 diabetes." (PMID 41502820, 2025). "In contrast, serum insulin levels were significantly elevated in sclerostin-overexpression mice, indicating the occurrence of insulin resistance." (PMID 40149867, 2025). "PTDM is characterized by reduced insulin secretion and insulin resistance, which are also manifested in type 2 diabetes mellitus (T2DM)." (PMID 40492760, 2025). "Chronic coffee consumption was shown to improve glucose tolerance, lower fasting blood glucose levels, and enhance insulin sensitivity in a high-fat-diet (HFD)-induced insulin resistance mouse model." (PMID 40565007, 2025).
Insulin resistance (continued). "When insulin resistance is present, it can disrupt the communication between insulin and leptin receptors, leading to impaired leptin signaling and reduced sensitivity to its effects on appetite regulation and energy balance." (PMID 40087612, 2025). "A key mechanism also involves insulin resistance, highlighted by elevated serum C‐peptide levels, a sign of increased insulin production found in insulin‐resistance cases, which has been specifically associated with CRC development." (PMID 39361532, 2025). "This contributes to insulin resistance and reduced insulin production, which are key in T2D development." (PMID 40834023, 2025). "Liver cirrhosis with portosystemic shunts and/or reduced hepatic mass impairs insulin clearance in the liver, resulting in insulin resistance due to chronic hyperinsulinemia." (PMID 40297825, 2025). "Insulin resistance [IR] refers to a condition in which cells exhibit reduced sensitivity to insulin, resulting in elevated blood glucose levels." (PMID 40002645, 2025). "These inflammatory kinases promote insulin resistance by negatively regulating key components of the insulin signaling cascade, such as the insulin receptor and insulin receptor substrate (IRS)." (PMID 40004236, 2025). "SCFAs influence insulin sensitivity and gluconeogenesis, while increased LPS levels contribute to systemic inflammation and insulin resistance." (PMID 40216734, 2025). "Prolonged exposure to elevated glucocorticoids not only disrupts insulin's glycemic control but also induces insulin resistance, leading to persistent hyperglycemia and excessive fat accumulation." (PMID 40177085, 2025). "In response to insulin resistance, pancreatic beta cells increase insulin secretion, resulting in compensatory hyperinsulinemia." (PMID 41309777, 2025). "Studies have found that the decrease of estrogen in postmenopausal women leads to a decrease in insulin sensitivity and is prone to insulin resistance, which also affects lipid metabolism." (PMID 40520783, 2025). "In the metabolic phenotype of PCOS with high insulin resistance, all these disturbances are even more pronounced, as insulin stimulates androgen synthesis and increases its free fraction by reducing SHBG production." (PMID 40362363, 2025). "The present study used the HOMA-IR equation, which relies on fasting glucose and insulin values to estimate hepatic insulin resistance, and the Matsuda index, which uses data from an OGTT to estimate whole-body insulin sensitivity." (PMID 39940348, 2025). "Type 2 diabetes mellitus (T2DM) is a prevalent endocrine disorder characterized by hyperglycemia resulting from insulin resistance or inadequate insulin secretion." (PMID 40842498, 2025). "TNF-α induces insulin resistance by disrupting post-receptor insulin signaling pathways, originates from adipose tissues, and acts as important cytokine in pro-inflammatory pathways." (PMID 40943380, 2025). "Biological mechanisms implicate chronic insulin resistance and hyperinsulinemia as key mediators of oncogenesis, partly through activation of insulin/IGF-1 signaling pathways and metabolic reprogramming." (PMID 40995175, 2025). "This form is characterized by insulin resistance in tissues and impaired insulin secretion due to beta-cell dysfunction, necessitating insulin therapy for disease management." (PMID 41387759, 2025). "Patients with T2DM and insulin resistance often exhibit reduced responsiveness to the insulin stimulation of glucose uptake in skeletal muscle, as well as a poor exercise performance and increased fat accumulation." (PMID 40141045, 2025). "Insulin resistance, a common hallmark of obesity and T2DM, is closely linked to alterations in the sialylation status of adipose tissue and other insulin-sensitive tissues." (PMID 41301440, 2025).
Insulin resistance (continued). "This is most likely due to the fact that insulin resistance is a pathological state in which impaired ATP production in mitochondria leads to a failure of pancreatic β cells to secrete a sufficient amount of insulin." (PMID 40806527, 2025). "Fasting insulin (FI) and insulin resistance (HOMA-IR): Fasting insulin decreased vs. Control in HIIT (MD −7.16 mIU/L, 95% CI −10.04 to −4.28) and A + R (MD −8.87 mIU/L, 95% CI −11.77 to −5.97)." (PMID 41370222, 2025). "The core pathological mechanism of T2DM is insulin resistance, where body cells become less sensitive to insulin, making it difficult to regulate blood glucose levels and resulting in hyperglycemia." (PMID 41459066, 2025). "ROS contribute to insulin resistance and impaired glucose metabolism by activating alternative signaling pathways that disrupt normal insulin function." (PMID 40732969, 2025). "TG and HDL-cholesterol are easily, routinely, and cost-effec-tively measured compared to insulin, making them useful for predicting insulin resistance." (PMID 41417532, 2025). "Insulin resistance (IR) is a complex metabolic disorder characterized by the body’s inadequate response to insulin, a crucial peptide hormone responsible for maintaining glucose homeostasis." (PMID 40278374, 2025). "SAC improves renal sodium reabsorption by reducing insulin secretion and decreases excessive sympathetic nervous system activation by improving insulin resistance." (PMID 41393949, 2025). "GLP-1 not only contributes to the regulation of insulin secretion and glucose metabolism, but also improves insulin resistance." (PMID 40351422, 2025). "For insulin sensitivity, MiR-27a has been shown to engage in the signaling networks important for glucose metabolism in insulin resistance." (PMID 39762333, 2025). "In this study, mid-dose PB supplementation resulted in notable improvements in insulin sensitivity and a decrease in ectopic lipid accumulation within the skeletal muscle, which is a key factor in ameliorating insulin resistance." (PMID 39861343, 2025). "Elevated serum insulin and insulin resistance impair sperm motility by inhibiting spermatogenesis through increased nuclear and mitochondrial DNA damage, and they also reduce semen volume and sperm count." (PMID 41327353, 2025). "Massive reductions in insulin doses in case 1 suggest resolution of insulin resistance, which can be more pronounced in people with AS than in controls." (PMID 40302276, 2025). "Among male patients with T2DM, two groups were identified, including the obesity-related phenotype with severe insulin resistance and the normal weight phenotype with improved insulin sensitivity." (PMID 39913381, 2025). "In comparisons based on vitamin D status, differences were particularly marked in body mass index (BMI), insulin, triglycerides, Homeostatic Model Assessment for Insulin Resistance (HOMA-IR), and Triglyceride-Glucose (TyG) Index." (PMID 41362334, 2025). "Within our model, elevated fasting insulin is an early marker of insulin resistance and β-cell compensation." (PMID 41590635, 2025). "Insulin resistance (IR) is a pathological state characterized by the attenuated response of insulin-sensitive tissues (skeletal and cardiac muscle, adipose tissue, and liver) to insulin signaling." (PMID 40591635, 2025). "Excess thyroid hormone increases the demand for glucose and insulin, which reduces the insulin sensitivity of the liver and eventually leads to insulin resistance." (PMID 41262264, 2025). "Cats with both DM and hypersomatotropism sometimes represent an important therapeutic challenge due to severe insulin resistance, often showing limited glycemic improvement despite high‐dose insulin therapy." (PMID 40853201, 2025). "Insulin resistance not only affects the glucose metabolism process but also interferes with insulin signaling in the central nervous system, thereby affecting the growth, survival, and function of nerve cells." (PMID 41341139, 2025).